CD47 (CD47 molecule)
Diseases named in the same sentence as CD47 in open-access papers (continued):
Sharing a sentence is not in itself a finding about the gene and the disease.
tumor (continued). "Enhances phagocytosis of tumor cells by binding to CD47 and altering the signaling pathway mediated by the complement system and the extracellular vesicles released by tumor cells." (PMID 40657202, 2025). "In the left tumor (distant tumor), the P1 monotherapy (15 mg/kg) group showed a certain degree of increase in tumor CD47 levels compared to the control group." (PMID 40733687, 2025). "In malignancies, CD47–SIRPα engagement provides a “don’t eat me” signal that inhibits phagocytosis of tumor cells." (PMID 41303525, 2025). "Activation of the CD47–SIRPα axis allows tumor cells to evade phagocytosis and escape immune surveillance, thereby promoting tumor progression." (PMID 40104289, 2025). "Blockade of the CD47/SIRPa axis has emerged as a promising approach to enhance macrophage-mediated anti-tumor activities in cancer immunotherapy." (PMID 41383500, 2025). "Research has demonstrated that combining BP with a CD47 antibody significantly suppresses cancer cell proliferation, yielding a synergistic anti-tumor effect." (PMID 40142970, 2025). "In this study, we constructed an oncolytic adenovirus designed to express an engineered SIRPα variant with an IgG1 Fc protein and investigated its therapeutic efficacy against CD47+ murine tumor cell lines both in vitro and in vivo." (PMID 40070841, 2025). "CD47 expression and tumor macrophage density were both highest in HNSCC compared to BC and CRC indications." (PMID 41415295, 2025). "Concurrently, the anti-CD47 antibody competitively binds CD47 on the tumor cell membrane, disrupting the CD47–SIRPα axis and lifting the “don’t eat me” signal, thereby enabling macrophage-mediated phagocytosis of the tumor cells." (PMID 40869279, 2025). "Sixteen hours later, we observed LNP-mediated transfection in parenchymal and tumor (human CD47+) cells." (PMID 40221395, 2025). "Tumor cells overexpress anti-phagocytic molecules such as the glycoprotein CD47, which engages SIRPα (Signal Regulatory Protein Alpha) on macrophages to inhibit phagocytic uptake and cytoskeletal rearrangement." (PMID 41373540, 2025). "Targeting the CD47-SIRPα interactions to enhance TAM-mediated phagocytosis of tumor cells holds significant promise for treating various tumors." (PMID 40075527, 2025). "CD47, expressed on the surface of tumor cells, binds signal regulatory protein α (SIRPα) on macrophages, preventing macrophage-mediated tumor clearance through phagocytosis." (PMID 40607438, 2025). "In the context of MSLN-targeted therapies, bsAbs have been engineered to simultaneously bind a tumor-associated antigen, such as MSLN, and a co-stimulatory receptor expressed on T-cells (e.g., CD3, CD20, CD47, CD137)." (PMID 41335396, 2025). "CD47 is mediated through its interaction with the SIRPα receptor on myeloid cells, to create an inhibitory signaling pathway that enables tumor cells to evade immune surveillance." (PMID 40548645, 2025). "Blockade of CD47 on tumor cells improved response to Cetuximab and radiation and showed efficacy in combination with Pembrolizumab in advanced solid tumors." (PMID 40121428, 2025). "Samples were stratified at the median CD47 expression level (by percent tumor cells positive) into CD47-high and CD47-low bins, and the C1QC gene signature score was plotted for each sample across indications." (PMID 41415295, 2025). "Thirdly, radiotherapy can upregulate the expression of immune checkpoints on tumor cell surfaces, such as CD47 and PD-L1." (PMID 40835598, 2025). "In line with this, co-culture of macrophages/neutrophils with ectopically expressed SIRP-β2 tumor cells results in an increased phagocytosis/trogocytosis treated with anti-CD47." (PMID 40560511, 2025). "The CD47–TSP-1 interaction inhibits tumor angiogenesis, reduces inflammation, and promotes stem cell regeneration." (PMID 40948940, 2025). "The combination of radiotherapy and CD47 blockade has been shown to be synergistic in reducing tumor growth and improving survival in animal models." (PMID 40356601, 2025).
tumor (continued). "Emerging combinations such as PD‐L1 × TGF‐β, PD‐1 × 4‐1BB, and CD47 × PD‐L1 illustrate opportunities to integrate immune modulation with tumor‐intrinsic pathway inhibition." (PMID 41388342, 2025). "The number of CD47+ cells increased in a dose-dependent manner, with a larger percentage of tumor cells with elevated CD47 expression when a higher MOI of NDV was used." (PMID 41322194, 2025). "Our findings demonstrate that maplirpacept is an effective CD47 blocker, able to trigger macrophage-mediated phagocytosis of all hematological tumors tested in vitro and control tumor burden in vivo." (PMID 40078999, 2025). "ALX148 binds CD47 from multiple species with high affinity, inhibits wild-type SIRPα binding, and increases macrophage phagocytosis of tumor cells." (PMID 40508145, 2025). "The basic strategy is to obtain a reagent focusing its activity prevalently around the cells expressing CD38, which enables avidity-induced blocking of CD47 on the same cells, in this way avoiding unwanted off-tumor effects." (PMID 40013150, 2025). "It will be intriguing to quantify CD47 expression following anti-CD47 blockade as this will hypothetically result in decreased CD47 expression as CD47+ tumor cells are phagocytosed." (PMID 41415295, 2025). "Here, we report a rationally designed aptamer-siRNA chimera that selectively targets intratumoral Treg cells by exploiting their co-expression of PD-L1 and CD47 within the tumor microenvironment." (PMID 41402667, 2025). "The chaperone glucose-regulated protein 78 (GRP78/BiP) is a master regulator of UPR and has also been shown to modify CD47 expression and tumour growth, suggesting a potential bidirectional role." (PMID 40133488, 2025). "Block the CD47 ‐ SIRPα signaling pathway and increase the activity of phagocytes to enhance phagocytosis of tumor cells." (PMID 40657202, 2025). "To examine the impact of HDACi-stimulated CD47 on the pro-tumor characteristics of macrophages, we co-cultured macrophages with HDACi-challenged CRC cells." (PMID 39994810, 2025). "Combining CD47 inhibitors with PD-1/PD-L1 blockade has shown synergistic anti-tumor effects in preclinical studies." (PMID 40177538, 2025). "The delivery of CD47, such as RS17, via EVs can block this CD47-SIRPα interaction, thereby targeting tumor cells and modulating tumor-associated macrophage (TAM) phenotypes." (PMID 40317075, 2025). "Dysregulation of the TSP1/CD47 axis promotes tumor progression through immune evasion and inhibits antitumor T cell responses." (PMID 41303525, 2025). "The upregulation of CD47 expression by SREBP1 inhibited the phagocytosis of tumor cells, resulting in a reduction in the infiltration of immune effector cells, which in turn promoted tumor immune evasion in ccRCC." (PMID 40548645, 2025). "We then evaluated the effect of CD47‐targeted NIR‐PIT maintenance therapy on tumor recurrence in mice." (PMID 40385528, 2025). "THBS1 can modulate innate and adaptive immune cells through a CD47-dependent mechanism, restricting anti-tumor immune responses." (PMID 41174721, 2025). "This activation leads to the release of cytokines from tumor stem cells, triggers CD47 expression in lung adenocarcinoma cells, and ultimately inhibits the phagocytosis of tumor cells." (PMID 40066231, 2025). "CT26 tumor cells treated with oAd-CD47 were co-cultured with CAR-Ms to evaluate the phagocytic activity of CAR-Ms." (PMID 40814015, 2025). "Collectively, this study reveals a mechanism underlying CD47 upregulation in tumor cells and highlights the potential of targeting the FUT8-SMURF1-CD47 axis as a therapeutic strategy to improve anti-tumor immune responses." (PMID 41355073, 2025). "Radiotherapy-induced effects are mainly related to radioresistance by upregulation of CD47 or SIRPα, but other studies demonstrated that it can also induce tumor cells sensitivity to radiotherapy by inhibiting CD47 expression." (PMID 40835598, 2025).
tumor (continued). "Blocking the CD47–SIRPα interaction reactivates macrophage-mediated phagocytosis and enhances anti-tumor responses." (PMID 41142826, 2025). "Depletion of CD47 has been shown to restore macrophage-mediated phagocytosis of tumor cells and suppress GBM growth, highlighting the therapeutic potential of targeting the CD47/SIRPα axis." (PMID 40800581, 2025). "Further analysis revealed that immune checkpoint genes CD47, PVR, SIRPA, and VTCN1 were found to be elevated in the high-risk cohort, indicating their role in suppressing anti-tumor immunity." (PMID 40243557, 2025). "Overexpression of MLKL upregulates CD47 expression via IL-6 signaling, which consequently suppresses macrophage phagocytosis and enhances tumor immune evasion." (PMID 41267084, 2025). "For KP1 tumors in NSG mice, we find ICD decreasing with tumor size in combined anti-CD47 and RT treatment, consistent with the trend in MC38 tumors in WT mice." (PMID 41296731, 2025). "Beyond phagocytosis-related antitumor immune response, the anti-CD47/SIRPα axis also enhances tumor cells sensitivity to radiotherapy through phagocytosis-independent mechanisms." (PMID 40835598, 2025). "Both Abs also increase phagocytosis in combination with tumor-opsonizing Abs, including a highly differentiated anti-CD47 Ab (AO-176) currently evaluated in phase I clinical trials." (PMID 40508145, 2025). "On the other hand, CD47-SIRPα pathway blockers were found to enhance the ability of macrophages to attack tumor cells, as it is stated that CD47 is overexpressed on cancer cells and inhibits macrophage-mediated phagocytosis." (PMID 40933989, 2025). "Further, dual-targeting fusion protein against PD-L1 and CD47 inhibits TNBC by enhancing anti-tumor immunity and disrupting immune evasion mechanisms." (PMID 40933989, 2025). "Preclinical studies have illustrated its high‐affinity binding to CD47, enhancing macrophage‐mediated phagocytosis of tumor cells." (PMID 40657202, 2025). "It has been shown that inhibition of CD47 with monoclonal antibodies suppressed tumor growth and effectively eliminated CSCs across various malignancies." (PMID 41233805, 2025). "This dual-binding mechanism facilitated the formation of a two-way adaptors between macrophages and tumor cells, promoting M1 polarization of TAMs and disrupting the CD47–SIRPα signaling axis to restore macrophage phagocytic activity." (PMID 41035884, 2025). "The anti-tumor function of macrophages can be activated by low dose-radiotherapy or through the removal of the “don’t eat me” signal CD47 on tumor cells, which can be recognized by the receptor signal regulatory protein α (SIRPα) on macrophages." (PMID 41375050, 2025). "Western blot analysis using tumor lysates showed that TRAF2 knockout significantly reduced CD47 levels in response to rapamycin." (PMID 39665172, 2025). "Next, we assessed the antitumour efficacy of IR700@Nb289‐OMVs plus NIR irradiation and CD47 nanobodies using the same tumour model." (PMID 40240911, 2025). "To test the relationship between tumor macrophages and CD47 expression, we evaluated the correlation between the TAM gene signatures and CD47 IHC data on samples that passed RNA-Seq quality control (HNSCC (n=36), BC (n=37), and CRC (n=36))." (PMID 41415295, 2025). "Increased staining comprised both intensity and prevalence, which was 100% in the liver metastases (as defined as >1% CD47 positive tumor cells)." (PMID 41415295, 2025). "CD47 expression measured with the digital algorithm demonstrated increased expression on tumor cells compared to the surrounding stromal cells." (PMID 41415295, 2025). "In the immune response, tumor cells exhibit high levels of CD47 expression, which impedes phagocytosis by macrophages through its binding to SIRPα on the macrophage surface, thereby facilitating immune evasion." (PMID 40598593, 2025). "In in situ xenografts of human and mouse CD47-homozygous-knockout GBM cells, the loss of CD47 function increases TNC expression levels in tumor cells." (PMID 40046232, 2025).
tumor (continued). "Expression of CD47 was rapidly upregulated in all the three tumor cell lines evaluated, with peak expression observed 12 h post-infection." (PMID 41322194, 2025). "Subsequently, abnormally structured blood vessels within the tumor tissue (such as leaky vasculature) facilitate tumor cell entry into the bloodstream; circulating tumor cells can express CD47, among other molecules, to evade phagocytosis by macrophages." (PMID 41230330, 2025). "Given the high levels of CD47 expression in CRC liver metastasis compared to primary tumors, we utilized the Tempus RWE dataset to reinvestigate the prognostic impact of CD47 once tumor location was accounted for." (PMID 41415295, 2025). "The CD24 and SIGLEC-10 axis is largely unchanged, however there is increased expression of CD47 on tumour cells and high levels of SIRPα on macrophages." (PMID 39788719, 2025). "CD47 on the tumor cell surface interacts with inhibitory macrophage receptor signal regulatory protein α (SIRPα) to send a signal that inhibits phagocytosis, preventing cancer cells from being cleared by macrophages." (PMID 40732268, 2025). "CD47, also known as the “don't eat me signal”, prevents tumor cell phagocytosis, promotes tumor progression, and allows cancer cells to avoid immune surveillance." (PMID 40723198, 2025). "In vitro and in vivo models have demonstrated that anti-CD47 treatment enhances phagocytosis by murine macrophages and boosts presentation of tumor-derived antigens via MHC I to OT-I T cells." (PMID 40800581, 2025). "In a GBM xenograft model, anti-CD47 treatment increased tumor cell phagocytosis from 2.7% to 13.3%, representing a 5-fold increase." (PMID 40845580, 2025). "In in vitro and in vivo models, the CD47 blocker ALX148 has been shown to stimulate anti-tumor properties of innate immune cells by promoting DC activation, macrophage phagocytosis, and shifting TAMs toward an inflammatory phenotype." (PMID 40508145, 2025). "PD-1 × CD47 bsAbs offer a coordinated approach to enhance both T-cell cytotoxicity and macrophage-driven tumor clearance, potentially leading to synergistic antitumor activity compared to monotherapies." (PMID 40508202, 2025). "Given that macrophages play a crucial role in phagocytosis—a key defense mechanism—tumor cells have been shown to evade macrophage‐mediated immune surveillance by exploiting ICMs such as PD‐L1 and CD47." (PMID 40433989, 2025). "Compared to the control group, the P1 monotherapy (15 mg/kg) group showed decreased CD47 levels in the right tumor (injected tumor)." (PMID 40733687, 2025). "For example, the CD47/SIRPα axis was identified in the late 1990s as the first tumor phagocytosis checkpoint." (PMID 40835598, 2025). "Mutating Y288 reduces CD47 levels, enhances phagocytosis, and limits tumour growth, while preventing CD47 ubiquitination has the opposite effect." (PMID 41195773, 2025). "CD47 functions as a “don’t eat me” signal, with its high expression in tumor cells inhibiting T cell function through the CD47-SIRPα pathway and promoting immune evasion." (PMID 40963634, 2025). "In contrast, loss of TRAF2 or autophagy induction promoted CD47 autophagic degradation and enhanced CD47 antibody anti‐tumor immunotherapy." (PMID 39665172, 2025). "A protein known as CD47 is involved in another biological pathway that regulates the interaction between tumor cells and TAMs." (PMID 40422244, 2025). "Patient-derived tumor xenografts model (PDX) was used to identify the CD47-SIRPα axis blocked therapy." (PMID 40523887, 2025). "CD47 is a “marker of self” overexpressed on numerous tumor cell membranes, inhibiting innate immune system attacks on hematologic and solid malignancies." (PMID 41350707, 2025). "For example, PPAB001, a bispecific antibody targeting CD47 and CD24, enhances anti-PD-L1 efficacy in TNBC by reprogramming tumor-associated macrophages to an anti-tumoral M1 phenotype." (PMID 40933989, 2025).
tumor (continued). "Studies on both in vitro and in vivo OS models indicate that anti-CD47 monoclonal antibodies can hinder the CD47-SIRPα signaling pathway, thereby bolstering the anti-tumor capabilities of macrophages." (PMID 40534850, 2025). "CD47 has been identified as a tumor antigen that is expressed by multiple human tumor types, including leukemia, lymphoma, myeloma, and certain solid tumors." (PMID 40578556, 2025). "RASON knockout significantly reduced CD47 expression, enhancing macrophage-mediated phagocytosis and anti-tumor immunity." (PMID 40128846, 2025). "For example, when evaluating CD47 as a potential predictive biomarker, tumor samples taken from primary tumor and liver metastases should be analyzed separately, given the significant difference of CD47 expression in these two tissue sites." (PMID 41415295, 2025). "By further modifying the RS17 peptides on the NPs, we increased their tumor-targeting capability and blocked the CD47–signal regulatory protein checkpoint, enabling macrophages to effectively phagocytose tumor cells." (PMID 40051791, 2025). "Among them, the CD47–SIRPα axis has emerged as a central mechanism by which tumor cells suppress macrophage-mediated phagocytosis." (PMID 41514569, 2025). "This upregulation increases the binding affinity of CD47 for SIRPα, consequently diminishing macrophage-mediated phagocytosis of tumor cells and facilitating immune escape." (PMID 40909948, 2025). "Cluster of differentiation 47 (CD47) delivers an inhibitory signal that suppresses phagocytosis and prevents immune clearance of tumor cells by interacting with signal regulatory protein alpha (SIRPα) on myeloid cells." (PMID 41131565, 2025). "Tumor cells evade macrophage phagocytosis by overexpressing CD47, which binds to SIRP-α on macrophages, transmitting a “do not eat me” signal." (PMID 40850976, 2025). "Enhances CRT expression while blocking CD47, and provides energy to phagocytes for phagocytosis and digestion of tumor cells." (PMID 40657202, 2025). "For example, oral delivery of gut anaerobic Bifidobacterium to mice caused its accumulation in the tumor microenvironment and enhanced the anti-tumor response of anti-CD47 immunotherapy via the stimulator of interferon genes (STING) pathway." (PMID 40927726, 2025). "Despite the moderate binding affinity to human CD47, maplirpacept drives enhanced macrophage-mediated phagocytosis of a wide variety of hematological tumor cells in vitro and reduces tumor burden in human xenograft models." (PMID 40078999, 2025). "Targeting CD47 in tumor cells has been a promising cancer treatment strategy, and its expression is regulated by several pathways, including the PI3K-AKT pathway." (PMID 40270598, 2025). "In cancer therapy, enhanced synthetic phagocytic receptors integrate FcRγ chain-driven CAR structures with secreted CD47 blockers, allowing macrophages to bypass tumor antigen heterogeneity." (PMID 41459510, 2025). "Pharmacological inhibition of acetyl-CoA metabolism via PDC-E2 blockade, as well as suppression of palmitate synthesis through FASN inhibition, resulted in a significant reduction in CD47 expression in tumour cells." (PMID 41163221, 2025). "Inhibit the expression of CD47 on the surface of tumor cells and bind to it to promote its internalization and digestion by phagocytes." (PMID 40657202, 2025). "More critically, CD47 interaction with SIRPα on myeloid cells initiates a “don’t-eat-me” signal that enables tumor cells to evade phagocytosis by macrophages and neutrophils." (PMID 40948940, 2025). "Given that SMYD3 regulates CD47 expression, we next explored the effects of CD47 on tumor growth and the infiltration of Th2 cells." (PMID 40548645, 2025). "This is consistent with known SIRPα expression on neutrophils and their ability to kill tumor cells following CD47/SIRPα blockade." (PMID 41171165, 2025).